IDH1 (isocitrate dehydrogenase (NADP(+)) 1)
Diseases named in the same sentence as IDH1 in open-access papers (continued):
Sharing a sentence is not in itself a finding about the gene and the disease.
tumor (continued). "In our report, the tumor cells from four cases showed positive for IDH1 (R132H), which were confirmed by sequencing techniques, and a noncanonical IDH1 R132G mutation was identified in Case #5 by Sanger sequencing." (PMID 35991838, 2022). "A study demonstrated that an inhibitor targeting IDH1-mutant conferred radiation resistance on IDH1-mutant tumor cells." (PMID 35436915, 2022). "The multivariate Cox regression results showed that the radiosensitivity-related risk score was an independent prognostic factor for LGG patients after adjusting for clinical factors such as age, sex, tumor grade, race, and IDH1." (PMID 35280808, 2022). "Through its oxidative decarboxylation activity, IDH1 promotes tumor progression and resistance to cell death through efficient fatty acid synthesis and ROS scavenging activities." (PMID 34764443, 2022). "An FDA-approved inhibitor of mutant IDH1, ivosidenib (AG-120), exhibited potent anti-wtIDH1 properties under low magnesium and nutrient levels, reflective of the tumor microenvironment in natura." (PMID 36153582, 2022). "Beads, Emulsion, Amplification and Magnetics (BEAMing) was used for the study of IDH1 mutations in plasma and correlated with the NGS results in the tumor." (PMID 35740557, 2022). "Genes with mechanistic links to IDH1 were involved in brain neuronal development, cell proliferation, cytokinesis, and O-mannosylation as well as tumor suppression and anaplerosis." (PMID 35877430, 2022). "Neomorphic IDH1/2 mutations and 1p/19q co‐deletions are the defining features of ODG, while CIC alterations are found in ~50–80% of these primary tumours." (PMID 34767259, 2022). "Despite this, IDH1 and IDH2 tumours have similar molecular ages suggesting that on average, tumours with IDH2 mutations have slower cell division rates." (PMID 36042521, 2022). "Here, with the benefit of a large patient cohort, we show that although IDH2 tumours are more commonly associated with TERT mutations, only IDH1 mutations in combination with TERT mutations are associated with significantly reduced survival." (PMID 36042521, 2022). "One hundred and seventy-seven patients were diagnosed to have grade IV GBM, 6 patients had grade III glioma with nonmutated IDH, and 15 patients were diagnosed by imaging only; therefore, their tumor grade and IDH1 status were indeterminate." (PMID 35371528, 2022). "Tumor cells with wild-type IDH1 and IDH2 were found to contain an average of 3.41 μg of 2-HG per gram of tumor tissue." (PMID 35154988, 2022). "Finally, in one of the IDH1-mutant cases, the Beads, Emulsion, Amplification and Magnetics (BEAMing) digital PCR technology detected one of the two IDH1 mutations that had been detected in the patient’s tumor sample in plasma, 7 years prior to its detection in blood." (PMID 35740557, 2022). "Abundant evidence suggested that IDH1 was functional in GBM progress while being regarded as a significant marker for the tumor classification." (PMID 35488886, 2022). "Initially, for the miR-array analysis, tumor samples from 24 GBM patients were available (Median age 62.2 years, 12 male and 12 female, IDH1/2 mutation in 1/24 patients)." (PMID 35486213, 2022). "With this history of multifocal recurrences, the tumor board recommended systemic therapy, and the patient initiated an IDH-1 blocker (ivosidenib) in March 2021." (PMID 35923675, 2022).
tumor (continued). "IDH1 mRNA and protein levels were found elevated in primary GB supporting the aggressive tumor growth and therapy resistance, while IDH1 inactivation promoted apoptosis and enhanced response to targeted therapies." (PMID 36361680, 2022). "Equivalent levels of IDH1 gene expression were observed for infiltrating tumor (5.7 ± 0.7), microvascular proliferation (5.56 ± 0.39), and pseudopalisading cells around necrosis (5.56 ± 0.64)." (PMID 35877430, 2022). "On the contrary, a direct relationship was found between tumor grading and the wild type status of IDH1-2 genes (p = 0.004)." (PMID 35872783, 2022). "Across the GBM tumor, IDH1 was differentially expressed, with higher levels observed in the cellular tumor (6.2 ± 0.69) and lower levels in the leading edge (4.85 ± 0.66; p-values < 0.05)." (PMID 35877430, 2022). "Although the GoF variants in IDH1 and IDH2 have been previously identified in the tumors of ~80% of individuals with OD and MS, their role in the tumor formation in these individuals is unclear." (PMID 36480544, 2022). "IDH was a key enzyme in the tricarboxylic acid cycle, and IDH1, IDH2 gene mutation status was associated with the prognosis of tumor patients." (PMID 36618415, 2022). "The univariate analysis showed that tumor recurrence, WHO grade, IDH1 wild-type, and high VASH1 expression were individual risk factors affecting the prognosis of LGG patients." (PMID 36504559, 2022). "Tumor progression and resistance to cell death are potentially promoted by IDH1 via its efficient fatty acid synthesis and ROS scavenging activities." (PMID 35877430, 2022). "While somatic mutations of IDH1 and IDH2 have been reported for several cancers, IDH3 mutations have rarely been detected in human tumours." (PMID 35744895, 2022). "Among the six patients with isocitrate dehydrogenase 1 (IDH1)-mutant tumors that were surveyed, circulating tumor DNA (ctDNA) was detected in PB in three of them (50%), at timepoints at which the patients were either untreated or exhibited progressive disease." (PMID 35740557, 2022). "The overall performance is measured by means of tumor segmentation accuracy, as well as by the merit figures of two RSs, one for tumor grading and the other one for isocitrate dehydrogenase‐1 (IDH1) status prediction." (PMID 35485596, 2022). "This pattern of IDH1 overexpression in GBM compared to non-tumor was confirmed in five additional GBM datasets (p-values < 0.05), where fold increases of between 1.15 and 1.3 were observed." (PMID 35877430, 2022). "Within the homogenous cohort of 24 IDH1/2wt patients older than 50 years with performed surgical resection of the tumor mass, 10 patients (41,6%) were evaluated positively and 14 were evaluated negatively for the presence of MGMT promoter methylation." (PMID 36361838, 2022). "Currently, in clinical work, prognosis is usually predicted by clinical parameters of LGG patients, such as tumor grade, histological classification, and IDH1 status." (PMID 35846118, 2022). "Upon hypoxia, tumor cells rely almost exclusively on glutamine-dependent reductive carboxylation catalyzed by IDH1 for lipids synthesis while, in normoxia, lipids are preferentially synthesized from glucose." (PMID 34764443, 2022). "Treatment of mutant IDH1 GBM bearing mice with either agent resulted in a dramatic loss of stem-like properties and decreased tumor growth." (PMID 34764443, 2022). "The reductive carboxylation activity of wild-type IDH1 also plays a crucial role in tumor cells located in hypoxic regions, which are frequently found in GBM and have been associated with tumor aggressiveness, invasion, and resistance to therapies." (PMID 34764443, 2022). "In a preclinical patient-derived IDH1 mutant xenograft tumor model study, compound 1 efficiently inhibited the production of the biomarker 2-HG." (PMID 36091829, 2022).
tumor (continued). "The results showed that both VASH1 and IDH1 were independent predictors of prognosis in LGG patients, and high VASH1 expression was significantly correlated with IDH1 wild-type status, while further reflecting tumor progression and recurrence status." (PMID 36504559, 2022). "The level of tumor mutational burden (TMB) was higher in the high-risk group, while more mutation of IDH1 was observed in the low-risk group." (PMID 36437961, 2022). "In fact, accumulation of D2HG in tumor cells is sufficient to establish the global hypermethylation landscape characteristic of mutant IDH1/2 GBM." (PMID 34764443, 2022). "In the last years, the therapeutic potential of several mutated IDH1/2 (mIDH1/2) inhibitors has been intensively investigated to counteract this neomorphic activity and reduce D2HG levels in tumours." (PMID 35744895, 2022). "The high ascorbate group also contained all three IDH1 mutant tumours, which are known to have a better prognosis." (PMID 35419292, 2022). "IDH1 gene expression (mean ± stdev) was significantly overexpressed in adult primary GBM (11.52 ± 0.59) compared to non-tumor (8.85 ± 0.27) in the TCGA-GBM dataset (p-value = 5.4 × 10−16), as previously reported." (PMID 35877430, 2022). "Using all relevant feature selection and random forest classification, three multiregional radiomics models were constructed to predict the status of IDH1 from the tumor core, the whole tumor, and all regions." (PMID 36290819, 2022). "Recent identification of neomorphic IDH1/2 mutations in secondary GBM has generated robust research to elucidate their role in gliomagenesis, tumor progression and impact on clinical outcome." (PMID 34764443, 2022). "During treatment, mutations in the IDH1 and ATRX genes are used to determine the grade and aggressiveness of a tumour, whereas the MGMT status is used to determine if treatment with DNA alkylating agents such as TMZ would be worthwhile." (PMID 35681582, 2022). "In one tumor, however, the percentages of the lost alleles on 1p and 19q were more than 10% lower than the expected values calculated from the TERT and IDH1 MAFs, possibly suggesting 1p/19q codeletion as the initial clonal event in this particular tumor." (PMID 35361262, 2022). "An important finding of that work was that G-CIMP encompassed almost all cases of tumours with the IDH1 (isocitrate dehydrogenase 1) dominant R132H gain-of-function mutation." (PMID 35055016, 2022). "The SB model has been recently used to study the impact of the tumor microenvironment, specifically the role of myeloid cell immunosuppression on mutant IDH1 tumor growth." (PMID 35978801, 2022). "By taking into account the clinical stages, we found that DLGAP1-AS1 was higher in IDH1 wildtype tumor than in IDH1-mutant tumor samples in WHO II, WHO III, and WHO IV patients." (PMID 35341001, 2022). "SIRT2 deacetylation is an important mechanism that regulates IDH1, which can exhibit tumour suppressor function by targeting the IDH1 K224 residue." (PMID 36101744, 2022). "For two patients with actionable alterations (FBXW7 deletion and pathogenic IDH1 mutation), the MTB prioritized other treatment options because of the availability of a tumor-entity-specific clinical trial and low VAF, respectively." (PMID 36139590, 2022). "First, samples were downloaded from the TCGA and CGGA databases, and information on the extent of tumor resection and IDH-1 status were unavailable." (PMID 36295489, 2022). "This methylation pattern varies according to key driver mutations; for example, the IDH1 R132H and H3F3A K27M mutations, and the location of the tumor." (PMID 34848827, 2022). "This indicates the sensitivity of this technology would at best be 5/60 (~8%) of cases with an IDH1 mutant tumor." (PMID 36380861, 2022). "This suggests that TERT mutations are context specific and only relevant to outcome predictions in IDH1 tumours." (PMID 36042521, 2022).
tumor (continued). "Further analysis revealed that risk characteristics, age, tumor grade, LGG diagnosis type, tumor type (primary and recurrent), and IDH1 (R132) mutation status independently served as prognostic indicators of LGG." (PMID 35937991, 2022). "Overview of correlation of tumour grade, IDH1, IDH2 and GNAS mutant profile pre‐ and postoperatively." (PMID 34528398, 2021). "Somatic mutations in the isocitrate dehydrogenase genes IDH1 and IDH2 occur at high frequency in several tumour types." (PMID 33740099, 2021). "While the methylation of the MGMT gene promoter helps to estimate the sensitivity of the tumor to alkylating agents such as TMZ, the relationship of IDH1/2 mutations with response to chemotherapy remains controversial." (PMID 33802571, 2021). "Tumor-derived mutant IDH1 suppresses wild-type IDH1 mainly by forming a catalytically inactive heterodimer, leading to a decline in cellular α-KG." (PMID 34707087, 2021). "An IDH1 (R132H)-specific peptide vaccine (IDH-1-vac) inducing a tumor-specific T helper cell response demonstrated efficacy in IDH-1(R132H)+ tumors in preclinical models and a first-in-man clinical trial." (PMID 34359606, 2021). "This indicates that the upregulation of IDH1 can reprogram the metabolic state of tumor cells, enhancing tumor growth and chemoresistance." (PMID 34234856, 2021). "Although studies have shown that small molecule inhibitors targeting IDH1-R132H have been effective in impairing tumor progression as monotherapy in pre-clinical models, in phase I clinical trials they have not been effective as monotherapies (NCT02381886)." (PMID 34168976, 2021). "Mutations in the genes for IDH1 and IDH2 have now been identified in more than 20 different neoplasms." (PMID 35028610, 2021). "In patients with wild-type IDH1, the clinical outcomes of patients with tumor-SVZ distance from 0 to 10 mm were worse than those with tumor-SVZ distance >10 mm." (PMID 34490090, 2021). "The main targetable genetic aberrations (IDH1 and BRAF mutations, FGFR fusions, HER2 amplification) can be identified in circulating tumour DNA (ctDNA) in around 20% of BTC patients." (PMID 33660222, 2021). "The major finding of our study is the significant correlation between IDH-1 status and the edema to tumor ratio." (PMID 33868245, 2021). "One of the major findings of our analysis is the positive correlation between IDH-1 wildtype and a higher edema to tumor ratio." (PMID 33868245, 2021). "Overexpression of PLAU/PLAUR was found to be significantly associated with clinical variables including age, tumor type, WHO grade, histology, IDH-1 mutation, and 1p19q status." (PMID 35087738, 2021). "Staining using a mutation-specific (R132H) antibody against IDH1, indicative for IDH-mutated astrocytomas and oligodendrogliomas reveals a specific reaction in the present tumor." (PMID 33625551, 2021). "H&E staining of tumor of tumor-bearing mice showed that the number of tumor cells in tumors of IDH1 overexpressed mice decreased, suggesting that their tumor activity decreased." (PMID 33867843, 2021). "We screened the catalogue of somatic mutations in the cancer (COSMIC) database, extracted IDH1/2 hotspot mutation data (IDH1R132, IDH2R172 and IDH2R140) and stratified them by tumour organ site." (PMID 33740099, 2021). "Activation of NIMA kinases, which induce premature mitosis, is highly activated in tumours with IDH1 wild-type." (PMID 34205437, 2021). "Multivariate analysis showed WHO grade IV, SVZ involvement, tumor-SVZ distance from 0 to 10 mm, IDH1 mutation, gross total resection, and chemotherapy serve as independent predictors of OS." (PMID 34490090, 2021). "ctDNA for IDH1/2 and GNAS mutations was detected pre‐operatively in a total of 30/81 (37%) patients harbouring the relevant hot spot mutations in their tumours." (PMID 34528398, 2021).
tumor (continued). "AG-881 is a small molecular inhibitor of IDH1 and IDH2 mutations, oral administration can reduce the formation of tumor metabolite 2-HG." (PMID 33981605, 2021). "We had previously demonstrated that the expression of MEOX2 in the tumor tissue correlates with its methylation profile and with wild-type IDH1/2." (PMID 34885053, 2021). "This discovery also triggered multiple studies investigating the effect of targeted mutant IDH1/2 inhibition in gliomas and other tumor types, and a number of pan and specific mutant IDH inhibitors are in clinical trials." (PMID 33668509, 2021). "We found that the expression of UGT2B4 was positively associated with expression of multiple well-known oncogenes such as SPINK1, IDH1, MYC, and SRC and negatively associated with expression of well-known tumor suppressors such as CIC and ERF." (PMID 33391440, 2021). "An IDH1(R132H)-specific peptide vaccine (IDH1-vac) induces specific therapeutic T helper cell responses that are effective against IDH1(R132H)+ tumours in syngeneic MHC-humanized mice." (PMID 33762734, 2021). "Previous studies identified age, the extent of the tumor resection, and the expression of specific genes, including Ki-67 and the isocitrate dehydrogenase 1 (IDH1), as indicators for OS." (PMID 34540662, 2021). "For example, thus far only three tumor subtypes, four cancer stem cell transcriptional states and a few biomarker-based predictors of therapy response (MGMT methylation and IDH1 mutation) have been described." (PMID 33919246, 2021). "IDH1 R132 promotes tumor progression and treatment tolerance, which can be mainly attributed to its abnormal metabolite 2-hydroxyglutarate." (PMID 34234856, 2021). "The expression of IDH1 in the tumor tissues and corresponding adjacent tissues of the 125 CRC patients was determined using immunohistochemistry." (PMID 34234856, 2021). "A previous study 38 and our data showed that unmutated IDH1 was highly expressed in tumor tissues and was accompanied by an increase in the production of α-KG and NADPH." (PMID 34234856, 2021). "IDH1 mutant tumor cells rely on glutaminase (GLS) activity to maintain α-KG homeostasis, making GLS inhibition a good therapeutic target." (PMID 34067729, 2021). "Findings have also revealed good correlation between mutations found in GBM, e.g., PDGFRA, IDH1, EGFR, and NF1—and the tumor’s metabolic fingerprint." (PMID 34068300, 2021). "Regarding the IDH1 gene, we found that it is overexpressed in all clinical samples and correlates with the grade of the tumor." (PMID 34573317, 2021). "For the first time, luminal A tumours were characterised by increased expression of hBCATm and IDH1." (PMID 33367952, 2021). "The relationships between IDH1 mutation and MGMT promoter methylation with the type of chemotherapies were also assessed independently with tumor recurrence interval." (PMID 34257620, 2021). "Immunohistochemistry for IDH1-R132H was done on 5-μm thick formalin-fixed, paraffin-embedded tumour sections with the use of an antibody specific for the mutant IDH1-R132H protein." (PMID 34601991, 2021). "Cluster 1A Krebs cycle-related tumours are secondary to mutations in SDHx, FH, MDH2, GOT2, SLC25A11, DLST or IDH1/2." (PMID 34834591, 2021). "IDH1 expression is elevated in various tumor types, including osteosarcoma, lung cancer, or gastric cancer, compared with normal tissues 12-14." (PMID 34234856, 2021).